CNTN1 (contactin 1)
Diseases named in the same sentence as CNTN1 in open-access papers (continued):
Sharing a sentence is not in itself a finding about the gene and the disease.
prostate carcinoma (9 papers, 2020 to 2024). A carcinoma that arises from epithelial cells of the prostate gland. "In prostate cancer, CNTN1 downregulates E-cadherin, leading to enhanced invasion and xenograft tumor formation." (PMID 39595172, 2024). "Contactin 1 (CNTN1) is a new oncogenic protein of prostate cancer (PC); its impact on PC remains incompletely understood." (PMID 33578925, 2021). "CNTN1 expression was more easily detected in prostate cancer cells, in both primary tumors and metastases, than in normal prostate glands or paracancerous tissues." (PMID 33194679, 2020). "This possibility is supported by CNTN1-mediated promotion of prostate cancer metastasis as prostate cancer predominantly metastasizes to the bone." (PMID 32752094, 2020). "CNTN1, which is also a cell adhesion protein, can promote the invasion of prostate cancer cells, enhance Akt activation, and reduce the expression of epithelial cadherin in cancer cells." (PMID 33194371, 2020). "In transgenic mice injected with prostate cancer cells overexpressing CNTN1, xenograft tumorigenesis, lung metastases, and metastatic nodules were increased." (PMID 33194679, 2020). "In summary, the role of CNTN1 in tumor proliferation varies across different tumors although it appears inconsistent in prostate cancer." (PMID 33194679, 2020). "In prostate cancer, CNTN1 upregulation occurs in cancer stem cells and primary cancer." (PMID 33578925, 2021). "However, in vitro knockdown of CNTN1 inhibited cancer cell proliferation, colony formation, migration, and invasion, whereas overexpression of CNTN1 increased tumor xenograft formation and metastasis in prostate cancer." (PMID 33194679, 2020). "Furthermore, knockdown of CNTN1 in prostate cancer cell lines also inhibited the PI3K/AKT pathway and suppressed the EMT process via concomitant upregulation of E−cadherin and downregulation of N-cadherin and vimentin." (PMID 33194679, 2020). "The expression of CNTN1 was upregulated in PCSCs compared to non-stem prostate cancer cells with a concurrent downregulation of E-cadherin." (PMID 32752094, 2020). "Clinically, while CNTN1 expression was negative or low in normal prostate glands, it was upregulated in advanced prostate carcinomas and are clearly present in both primary prostate tumors and matched lymph node and bone metastasis." (PMID 32752094, 2020). "CNTN1 increases tumor cell invasion, migration, and metastasis by promoting EMT via activation of the PI3K/AKT pathway, downregulation of E-cadherin, and upregulation of N-cadherin and vimentin in lung and prostate cancers." (PMID 33194679, 2020).
hepatocellular carcinoma (8 papers, 2018 to 2024). A malignant tumor that arises from hepatocytes. "CNTN1 has been reported to associate with poor prognosis in patients with lung, esophageal and oral squamous cell carcinomas, and hepatocellular carcinoma." (PMID 33578925, 2021). "The expression level of CNTN1 showed a clear association with clinicopathological parameters and poor prognosis in many cancers including lung, gastric, prostate, astrocytic gliomas, stomach, thyroid cancers, hepatocellular carcinoma (HCC) and oral squamous cell carcinoma (OSCC)." (PMID 32752094, 2020). "In hepatocellular carcinoma (HCC) tissues, CNTN1 overexpression was also reported to be closely associated with aggressive clinicopathological features, suggesting that CNTN1 may be involved in tumor metastasis and invasion in HCC." (PMID 29673312, 2018). "In hepatocellular carcinoma (HCC), CNTN1 expression was markedly increased in HCC tumors and this upregulation was correlated with tumor size and TNM stage." (PMID 32752094, 2020). "Similarly, the expression of CNTN1 protein was found in 81% and 54.4% of 100 thyroid cancer tissues and 90 hepatocellular carcinoma (HCC) samples, respectively." (PMID 33194679, 2020).
glioma (7 papers, 2010 to 2024). A benign or malignant brain and spinal cord tumor that arises from glial cells (astrocytes, oligodendrocytes, ependymal cells). "Interestingly, low-grade glioma demonstrates the reverse phenotype, similar to our findings in neuroblastoma, where high CNTN1 is associated with increased overall survival." (PMID 39595172, 2024). "Further, CNTN1 is identified as a novel immunogenic tumor-associated antigen in IDH-mutant gliomas." (PMID 33194679, 2020). "Contactin 1 (CNTN1), for example, has already been proposed as a key factor in glioma dissemination and its expression tends to be increased in several brain tumours." (PMID 20885975, 2010). "Contactin-1, tenascin-C and tenascin-R have adhesion and migration effects in glioma cells." (PMID 25238264, 2014). "CNTN1 was identified as a TAA along with other four TAAs (CRKII, CFL1, NME2, and TKT) in IDTH1-mutant lower grade gliomas through a proteomic and immunologic approach." (PMID 32752094, 2020). "In line with this, endogenous contactin-1 from E98 cells indeed bound to PTPRZ-B ecto-VSV that was preloaded onto anti-VSV antibody-coupled beads, underscoring PTPRZ-B – contactin-1 interplay in E98 glioma cells." (PMID 25238264, 2014). "In our glioma models, PTPRZ-contactin-1 interactions apparently lead to migratory responses." (PMID 25238264, 2014). "CNTN1 triggered the activation of endogenous T cells in a substantial proportion for up to 56% of patients with astrocytic and/or oligodendroglial IDH1-mutant lower grade gliomas, but none in healthy donors." (PMID 32752094, 2020).
thyroid cancer (7 papers, 2020 to 2024). "Functionally, CNTN1 silencing in vitro restrained thyroid cancer cell migration and invasion abilities." (PMID 32752094, 2020). "Another study demonstrated that CNTN1 was upregulated in thyroid cancer, and knocking down of CNTN1 could inhibit the proliferation, migration, and invasion through regulating the Notch pathway." (PMID 38562021, 2024). "Moreover, in thyroid cancer, knockdown of CNTN1 decreases tumor cell proliferation and invasiveness by reducing cyclin D1 expression." (PMID 39595172, 2024). "Indeed, silencing or inhibition of CNTN1 in experimental models have already highlighted its suitability as a potential target in lung, gastric, prostate, thyroid cancers, and oral squamous cell carcinoma." (PMID 32752094, 2020). "Additionally, CNTN1 was positively correlated with the late TNM stage in thyroid cancer tissues." (PMID 33194679, 2020). "The knockdown of CNTN1 suppresses cellular proliferation and invasion in thyroid cancer and also inhibits the expression of cyclin D1 (CCDN1), a Notch target gene, suggesting CNTN1 may participates in the tumor proliferation and metastasis in part via regulating the Notch pathway." (PMID 32752094, 2020). "CNTN1 was discovered as a potential RET-PTC3 downstream gene in GEO profile database and RET inhibitor regorafenib successfully downregulated CNTN1 expression in thyroid cancer cells." (PMID 32752094, 2020). "Moreover, knockdown of CNTN1 significantly repressed the expression of cyclin D1 (CCND1), a target gene of the Notch1 pathway, indicating CNTN1 to potentially regulate the expression of CCND1 by activating Notch1 in thyroid cancer." (PMID 33194679, 2020).
Tremor (7 papers, 2021 to 2025). An unintentional, oscillating to-and-fro muscle movement about a joint axis. "Although nonspecific, the consistency of the early onset neuropathic tremor in out cohort mirrors the frequent tremor seen in CNTN1‐related paranodopathy." (PMID 39444079, 2025). "To gain a deeper understanding of the disease, we conducted a comprehensive literature review, identifying 52 cases of CNTN1 antibody-positive nodopathy to date, with a tremor prevalence of 26.9%." (PMID 38846936, 2024). "Our findings indicate a high prevalence of tremor (26.9%) and elevated CSF protein levels among patients with CNTN1 antibody-positive nodopathy." (PMID 38846936, 2024). "Other antibodies, including anti-neurofascin-140/186, anti-contactin-1, anti- contactin-1 associated protein (CASPR-1) have also been associated with CIDP and tremor in selected patients." (PMID 39474246, 2024). "A review of the literature revealed 52 cases of CNTN1 antibody-positive nodopathy, with 14 patients (26.9%) exhibiting tremor, suggesting it as a characteristic symptom of CNTN1-positive nodopathy." (PMID 38846936, 2024). "Our findings highlight a tremor prevalence of 26.9% among CNTN1 antibody-positive nodopathy cases and suggest that the CSF protein level in such cases may be significantly elevated compared to typical chronic inflammatory demyelinating polyradiculoneuropathy (CIDP)." (PMID 38846936, 2024). "Later, Yumako’s cohort, which included 13 CNTN1 antibody-positive patients out of 533 CIDP patients, reported two instances of tremor." (PMID 38846936, 2024). "Initially, Querol identified CNTN1 antibodies in CIDP patients, although none of the three cases exhibited tremor." (PMID 38846936, 2024).
autoimmune neuropathies (6 papers, 2021 to 2025). "CNTN1 is an axonal protein commonly associated with autoimmune neuropathies." (PMID 39835101, 2024).
Autoimmunity (6 papers, 2019 to 2025). The occurrence of an immune reaction against the organism's own cells or tissues. "Moreover, the damage caused by anti-contactin-1 in the first place could make the paranode more accessible to immune response and therefore trigger secondary autoimmunity against its interaction partner Caspr-1." (PMID 39434877, 2024). "Further research, including additional cases, is needed to confirm the potential link between CNTN1 autoimmunity and thymoma involvement." (PMID 40995362, 2025). "Clinical features of two autoimmune patients with nodopathy with anti-CNTN1 antibody after low-dose rituximab treatment." (PMID 35958552, 2022). "Recently evidence of autoimmunity toward neurofascin-155 (NF155) and contactin-1 (CNTN1) in some patients have been reported." (PMID 30941082, 2019). "Contactin 1 (CNTN1) is also described in the setting of autoimmunity, although not specifically within membranous lupus nephritis." (PMID 34899763, 2021). "Hence, the switch from contactin-1 to Caspr-1 is not explained by autoimmunity against complex epitopes or affinity maturation." (PMID 39434877, 2024).
esophageal cancer (6 papers, 2018 to 2022). A primary or metastatic malignant neoplasm involving the esophagus. "It is notable that the level of CNTN1 in esophageal cancer cells was associated with vascular endothelial growth factor C (VEGF-C) that induced the recruitment of C/EBPα to interact with CNTN-1 promoter." (PMID 31427725, 2019). "Compared to 30 normal esophageal tissue samples, 82 primary esophageal cancer tissue samples had a significantly increased expression of CNTN1 mRNA and an overall stronger immunohistochemical staining for CNTN1 protein." (PMID 33194679, 2020). "Recent study has shown that a reduction in CNTN1 expression alone was sufficient to reverse the enhanced migration ability of esophageal cancer cells attributable to ectopic VEFGC expression in vitro." (PMID 32752094, 2020). "This indicates a crucial role of CNTN1 as a downstream mediator of VEGF-C-induced migration in esophageal cancer." (PMID 29673312, 2018). "As well, ESCC tissues showed significant upregulation of CNTN1 expression compared to adjacent non-tumor tissues and this increased expression was positively correlated with ESCC stage, lymph node metastasis and lymphatic invasion, supporting CNTN1′s role in esophageal cancer progression." (PMID 32752094, 2020). "Furthermore, the transcription factor C/EBP is found to mediate the activity of CNTN1 associated with the VEGF-C/VEGFR-3 pathway in lung and esophageal cancers." (PMID 33194679, 2020). "Furthermore, the binding of C/EBP with the CNTN1 promoter was regulated by VEGF-C in esophageal cancer in vitro." (PMID 33194679, 2020). "Moreover, the aggravated tumor invasion and migration in esophageal cancer cells have been attributed to increased expression of VEGF-C that can be reversed by a reduction in CNTN-1 level." (PMID 31427725, 2019). "Moreover, in esophageal cancer cells, vascular endothelial growth factor C (VEGF-C) was shown to enhance tumor migration and progression, which was reversed by downregulation of CNTN1." (PMID 29673312, 2018).
melanoma (5 papers, 2016 to 2022). A malignant, usually aggressive tumor composed of atypical, neoplastic melanocytes. "This is consistent with CNTN1′s role as an activator of Notch signaling and the association of Notch1 activation with a more metastatic phenotype in primary melanoma cells." (PMID 32752094, 2020). "Recent evidence identified CNTN1 as a novel melanoma-associate biomarker." (PMID 32752094, 2020). "As well, CNTN1 was discovered to be a novel biomarker for melanoma, glioblastoma, and colorectal cancer." (PMID 32752094, 2020). "Moreover, CNTN1, a cell adhesion protein and a member of the immunoglobulin superfamily known to be expressed in melanoma, was highly upregulated in MTEX of some patients with NED/SD and was not detectable in MTEX of PD patients." (PMID 33613873, 2021). "Moreover, CNTN1 was hypermethylated, and its expression was downregulated in colorectal cancer and primary melanomas." (PMID 33194679, 2020). "In contrast, CNTN1 (contactin-1) was upregulated only in melanoma-specific sEVs of patients that did not progress." (PMID 35804857, 2022). "On the contrary, upregulation of TYRP1, CNTN1 and UCHL1 in melanoma could be reversing malignant conditions." (PMID 27206673, 2016). "Hence, the molecular signature of MTEX consisting of PDCD6IP/ALIX, 4 correlated proteins (HSP90AB1, TUBB, TUBB1, and PFN1) highly expressed in MTEX of patients with PD, plus CNTN1 and TGF‐β1 with differential distribution in MTEX of PD vs NED/SD patients may have prognostic significance in melanoma." (PMID 33613873, 2021).
oral squamous cell carcinoma (5 papers, 2012 to 2024). "In this study, a possible association between CNTN1 expression and clinicopathological parameters and clinical outcomes in patients with oral squamous cell carcinoma (OSCC) was examined." (PMID 22580838, 2012). "In a study investigating oral squamous cell carcinoma (OSCC), Flt-4 stimulation or inhibition directly resulted in upregulated or downregulated expression of CNTN1 respectively." (PMID 32752094, 2020).
gastric adenocarcinoma (4 papers, 2020 to 2024). "Next, 10 ERGs associated with prognosis of gastric adenocarcinoma patients are screened out by univariate Cox regression, and 6 pivotal prognostic ERGs (MMP8, MMP11, TFDP3, MYB, F2, and CNTN1) are identified through multivariate Cox regression." (PMID 32309437, 2020). "With that, we performed detailed OS analysis for all cancer types, significant association between elevated CNTN1 with reduced survival was identified in bladder urothelial carcinoma (BLCA), brain lower grade glioma (LGG) and stomach adenocarcinoma (STAD)." (PMID 32752094, 2020). "Two stage-salient genes, namely CNTN1 and BAI3 (ADGRB3) were documented as putative tumor suppressor genes involved in gastric adenocarcinoma, providing specific support for our findings." (PMID 39484215, 2024).
glioblastoma (4 papers, 2019 to 2025). The most malignant astrocytic tumor (WHO grade IV). "While normal astrocytes did not express CNTN1, glioblastomas showed an overexpression of CNTN1 protein and a positive association was identified between increasing malignancy grade and CNTN1 expression." (PMID 32752094, 2020).
myasthenia gravis (4 papers, 2016 to 2025). Myasthenia gravis (MG) is a rare, clinically heterogeneous, autoimmune disorder of the neuromuscular junction characterized by fatigable weakness of voluntary muscles. "Although a low-dose rituximab regimen was administered to patients with other autoimmune diseases, such as myasthenia gravis and neuromyelitis optica spectrum disorders, and satisfactory outcomes were obtained, this low-dose rituximab regimen has not been trialed in anti-CNTN1-positive patients." (PMID 35958552, 2022).
Nephropathy (4 papers, 2021 to 2025). A nonspecific term referring to disease or damage of the kidneys. "And we found that the antibody‐positive patients were all positive to anti‐CNTN1 antibody, which strongly suggested that there was a close relationship between anti‐CNTN1 antibody and nephropathy." (PMID 36932648, 2023). "Herein, we described co‐morbidity of CIDP/autoimmune nodopathies with nephropathy in seven patients, four of whom had positive anti‐CNTN1 antibody in the serum." (PMID 36932648, 2023). "Anti‐CNTN1 antibody was the most frequent antibody in this group of patients with CIDP/autoimmune nodopathies and nephropathy." (PMID 36932648, 2023). "In conclusion, the co‐morbidity of CIDP/autoimmune nodopathies and nephropathy was not rare and anti‐CNTN1 antibodies could be found in a high proportion of the cases." (PMID 36932648, 2023).
viral infection (4 papers, 2020 to 2025). "Since miR-200c was upregulated following virus infection, we confirmed the role of miR-200c in the regulation of CNTN1 and USP25 in miR-200c-deficient cells." (PMID 35171955, 2022). "Together, these results suggest that CNTN1 is a previously unappreciated host co-receptor for SARS CoV-2 that may potentiate viral infection." (PMID 35931765, 2022). "Our results showing that CNTN1 promotes ACE2-dependent infection echoes previous findings on NRP1, and further supports the existence of additional co-factors that promote viral infection." (PMID 35931765, 2022). "Particularly, the biological process related to the interaction of p7-CNTN1/GGNBP2 will be further explored, because there is less supporting evidence for effect of CNTN1 and GGNBP2 on viral infection in the literature." (PMID 33329485, 2020). "Confocal microscopy showed that CNTN1 and USP25 colocalized and dispersed throughout the cytoplasm without virus infection, which had a partial association with MAVS." (PMID 35171955, 2022). "Remarkably, our results show that Contactin-1, a previously unknown SARS CoV-2 spike-specific receptor that is upregulated in COVID-19 patients, significantly enhances ACE2-dependent pseudotyped virus infection." (PMID 35931765, 2022). "Therefore, it’s reasonable to speculate that another certain degradation mechanism, but not miR-200c targeted, was induced to downregulate CNTN1 protein upon virus infection." (PMID 35171955, 2022).
Anxiety (3 papers, 2023 to 2025). Intense feelings of nervousness, tension, or panic often arise in response to interpersonal stresses. "A recent study identified CNTN1 as a novel risk gene that induces anxiety and depression through functional actions in the hippocampus, which reduce neuronal growth and maturity." (PMID 38239902, 2023). "The time spent in the central arena during the OFT used to reflect the anxiety-like phenotype was significantly decreased by CNTN1 overexpression and this behavior was alleviated by minocycline (F5, 48 =6.26, P=0.0002)." (PMID 37196127, 2023). "Primarily, hippocampal CNTN1 overexpression triggered anxiety-like behavioral traits, with less time spent in the central arena in the OFT test by mice injected with AAV-CNTN1 than by the AAV-Control mice (F2, 25 =4.915, P=0.0158)." (PMID 37196127, 2023). "As a known physical interaction partner of Negr1, Cntn1, an immunoglobulin superfamily member, has been previously shown to increase in the hippocampus following chronic unpredictable stress, where its upregulation correlates with anxiety- and depression-like behaviors." (PMID 41440084, 2025).